PARP1 (poly(ADP-ribose) polymerase 1)
Diseases named in the same sentence as PARP1 in open-access papers (continued):
Sharing a sentence is not in itself a finding about the gene and the disease.
cancer (continued). "Olaparib is a selective inhibitor of the poly (ADP-ribose) polymerase (PARP) enzymes (PARP1 and PARP2), which works by taking advantage of the defect in DNA repair in cancer cells with BRCA mutations and inducing cell death." (PMID 39202767, 2024). "These adaptations by cancer cells reduce the effectiveness of PARP1 inhibitors over time, necessitating the development of combination therapies or novel inhibitors to overcome resistance." (PMID 39456202, 2024). "For instance, in cases where DSBs occur within cancer cells, cGAS relocates to the nucleus, thereby impeding the formation of PARP1–TIMELESS complexes, which inhibit homologous recombination (HR) repair and sustain CIN, thereby facilitating tumor evolution." (PMID 38817608, 2024). "Despite important advances in cancer treatment with PARP1 inhibitors, HR-proficient cancers are resistant to PARP1 inhibitors." (PMID 39679370, 2024). "The goal is to identify experimental conditions that maximize our confidence in how effectively PARP1 inhibitors shift this balance towards apoptosis in cancer cells, thereby providing insights into potential therapeutic strategies." (PMID 38956095, 2024). "PARP1, an extensively studied target for cancer therapy, plays a pivotal role in the DNA damage response by covalently transferring ADP-ribose from NAD+ to target substrates, producing poly (ADP-ribose) (PAR) polymers." (PMID 39174499, 2024). "Therefore, the cell-protective role of PARP-1 (against mild oxidative stress, as evident from this study) could have been implicated in those therapy-resistant cancer cells where cells survive in a dormancy stage (although they are metabolically active) but grow back with tumorigenic potential." (PMID 39294821, 2024). "These novelcompounds (DDNO derivatives) hold promise as potential PARP-1 inhibitorsfor the development of targeted therapeutics against cancer." (PMID 39346823, 2024). "Recently, the deficiency of ARID1A, a subunit of the SWI/SNF family, has been demonstrated to sensitize cancer cells to PARP1 inhibitors both in vitro and in vivo, rendering PARP1 an appealing target for MRT therapy." (PMID 38893160, 2024). "In conclusion, 180055 emerges as a promising clinical candidate with its remarkable ability to degrade PARP1 effectively and selectively, offering a potential new horizon for cancer therapeutics." (PMID 39695097, 2024). "It has emerged as a promising target for anti-cancer therapies, leading to extensive research on PARP1 inhibitors." (PMID 39598347, 2024). "The significant role of PARP-1 in cancer has been solidified by the development of numerous PARP inhibitors (PARPi) used as therapeutic agents either independently or in conjunction with other drugs." (PMID 38666920, 2024). "By inhibiting PARP‐1 activity, these inhibitors incapacitate DNA repair mechanisms, leading to the eradication of such cancers." (PMID 39102671, 2024). "For that reason, PARP-1 is one of the intriguing targets for cancer therapy where PARP-1 inhibitors showed efficiency in inducing cellular death." (PMID 38072913, 2024). "PARP inhibitors are effective in HR-deficient cancers, particularly BRCA1/2-mutated ones, by inhibiting PARP1 and blocking DNA repair processes." (PMID 39200270, 2024). "The development of DDR inhibitors, particularly targeting poly(ADP-ribose) polymerase 1 (PARP1), offers new strategies for enhancing the effectiveness of traditional cancer treatments and improving patient outcomes." (PMID 39456202, 2024). "After evaluating the synthetic lethality and underlying cellular stress responses in cancer cells with XRN2 depletion and PARP1 inhibition, we investigated the cell death pathway employed under these conditions." (PMID 38339346, 2024). "Poly (ADP-ribose) polymerase 1 (PARP1) is a crucial enzyme in the DNA repair pathway, making it a significant target for synthetic lethality in cancers with BRCA1 and BRCA2 mutations." (PMID 39768978, 2024).
cancer (continued). "In this work, we utilized a realistic PD model for PARP1-inhibited cell apoptosis in a model-guided optimal experimental design workflow to reduce uncertainty in the performance of cancer drug candidates." (PMID 38956095, 2024). "Given its biological importance and potential as a cancer drug target, PARP1 has become a focal point in oncology, and research on it has been intensifying." (PMID 38475878, 2024). "Preclinical studies show that PARP1 inhibition enhances radiosensitivity in cancer cells, and clinical trials confirm the effectiveness of combining PARP1 inhibitors with radiation therapy." (PMID 39796080, 2024). "PARP1 also functions as a sensor of oxidative stress and PARP1 inhibitors have been shown to enhance the sensitivity of cancer cells to chemotherapy." (PMID 38475878, 2024). "The inhibition of DTYMK can potentially enhance cancer cell sensitivity to PARP1 inhibitors by disrupting pyrimidine metabolism and amplifying DNA damage in cancer cells." (PMID 39195238, 2024). "More specifically, PARP1 suppression leads to accumulation of DNA errors and sensitizes cancer cells to death in the presence of conventional anti-cancer drugs options." (PMID 38740853, 2024). "Our data also revealed an increased sensitivity of cancer cells with low levels of PSIP1 to drugs that induce transcription-associated DNA damage and PARP1 inhibitors." (PMID 38191578, 2024). "In particular, the important role that PARP1 plays in the regulation of the DNA damage response (DDR) has been exploited therapeutically for cancer." (PMID 38360994, 2024). "The development of poly (ADP-ribose) polymerase inhibitors (PARPi) represents a novel approach to cancer treatment, targeting PARP1, PARP2, and PARP3 proteins crucial in repairing single-strand DNA breaks." (PMID 38910707, 2024). "This is a very exciting finding because the DNA repair protein poly-(ADP-ribose) polymerase 1 (PARP1) is a rather promising target for blocking in cancer." (PMID 39598347, 2024). "PARP1 expression levels are correlated with prognosis in patients with cancer, and high PARP1 expression predicts poor survival of patients with AML, while combined treatment using talazoparib and NL101 resulted in strong synergistic effects against AML." (PMID 39175540, 2024). "The use of PARP1 inhibitors in cancer therapy is believed to have a prospective future, however, there are few reports about PARP1 inhibitors of biological origin." (PMID 38332126, 2024). "It is obvious to complement this set of biomarkers by PARP-1 expression in order to select the tailored cancer therapy regimen." (PMID 39456536, 2024). "Upregulation of PARP1 is observed in cancers with BRCA gene defects and has been shown to enhance the resistance of cancers to DNA‐damaging therapies, hence making its inhibition an attractive field of study in pharmaceutical research." (PMID 38258328, 2024). "PARP-1 inhibitors, such as Olaparib-resistant tumours have been reported, which is a serious issue in cancer therapy." (PMID 39294821, 2024). "In this study, we investigated an approach for improved early detection of esophageal dysplasia and cancer using the DNA repair enzyme Poly (ADP-ribose) Polymerase 1 (PARP1) as imaging biomarker." (PMID 38383387, 2024). "This approach relies on the idea of synthetic lethality, where the inhibition of PARP1 in cancer cells with defective DNA repair mechanisms (such as BRCA1/2 mutations) leads to cell death, while normal ones with intact DNA repair pathways are less affected." (PMID 39456202, 2024). "Initially, it was believed that PARPis killed cancer cells by inhibiting the catalytic activity of PARP1." (PMID 39174499, 2024).
cancer (continued). "Our findings emphasize the potential translational significance of targeting XRN2 cancer vulnerabilities via PARPi given that PARP1 inhibition impairs its compensatory role in mitigating cellular stress created by XRN2 loss." (PMID 38339346, 2024). "Given its potential biological role in malignant tumors, PARP1 has emerged as a promising target for anticancer drugs." (PMID 39679370, 2024). "These challenges highlight the need for ongoing research to improve the specificity, safety, and efficacy of PARP1 inhibitors, as well as to develop strategies to mitigate viral activation and resistance development in cancer therapy." (PMID 39456202, 2024). "In this study we have provided preclinical data which show the potential of the PARP1-targeted imaging agent PARPi-FL for early detection of esophageal dysplasia and cancer lesions." (PMID 38383387, 2024). "PARP1, whose role in cancer we emphasized earlier, is also significantly reduced when exposed to combinations of aptamers." (PMID 39598347, 2024). "As a compensatory mechanism, the activity of PARP1, responsible for triggering the BER and NHEJ pathways, is frequently increased in HR-deficient cancer cells." (PMID 39195238, 2024). "PARP inhibitors olaparib and talazoparib, which generate tight, DPC-like complexes between PARP-1/2 and DNA, effectively induce cell death in cancer cells." (PMID 38084926, 2024). "Poly-ADP-Ribose Polymerase (PARP-1) is an overexpressed enzyme in several carcinomas; consequently, the design of PARP-1 inhibitors has acquired special attention." (PMID 38255943, 2024). "In this regard, HMGA2 was shown to physically interact with PARP1, which stimulates PARP1 enzymatic activity on alkylated DNA from cancer cells treated with MMS." (PMID 36980621, 2023). "The goal of this study is to enhance the efficacy of AF as a cancer treatment by combining it with the poly(ADP-ribose) polymerase-1 (PARP) inhibitor olaparib (referred to as ‘aurola’)." (PMID 36978917, 2023). "PARP1 is an enzyme involved in the repair of single-stranded DNA breaks, making PARP1 inhibitors prominent in cancer therapy." (PMID 36900195, 2023). "Since it has been shown that inhibiting PARP1 makes cancer cells more responsive to radiotherapy, PARP1 inhibitors are being created." (PMID 37808268, 2023). "These molecularly targeted drugs induce cancer cell death by inhibiting Poly (ADP-ribose) polymerase-1 (PARP-1), which promotes the repair of DNA single-strand breaks." (PMID 37345021, 2023). "It appears that excessive PARP1 activation is involved in a specific cell death pathway called parthanatos, while inhibition of PARP1 in cancer cells amplifies DNA damage to a lethal level." (PMID 36743979, 2023). "In sharp contrast, PARP1 inhibitors are in clinical use for the eradication of vulnerable cancer cells." (PMID 36743979, 2023). "Poly(ADP-ribose) polymerase-1 (PARP1) is a potential biomarker and therapeutic target for cancers that can catalyze the poly-ADP-ribosylation of nicotinamide adenine dinucleotide (NAD+) onto the acceptor proteins to form long poly(ADP-ribose) (PAR) polymers." (PMID 37375313, 2023). "In conclusion, this study identifies the utility of PARP-1 inhibition as a means for delivering lethal high-LET Auger radiation to the cancer cell’s DNA resulting in tumor-specific DNA damage and cytotoxicity." (PMID 36834491, 2023). "PARP1, an established anti-cancer target that regulates many cellular pathways, including DNA repair signaling, has been intensely studied for decades as a poly(ADP-ribosyl)transferase." (PMID 37116497, 2023). "Nevertheless, the explanation is difficult since we found a better survival for patients with high EVI1 and high PARP1 protein expression, which would imply protection of apoptosis of cancer cells and therefore rather expect worse survival." (PMID 37525239, 2023).
cancer (continued). "electroporated the CRISPR-Cas9 plasmid and sgRNA into SKOV3 cancer cell-derived exosomes to target the poly (ADP-ribose) polymerase-1 (PARP-1) gene in SKOV3 tumor cells and SKOV3 xenograft mice." (PMID 37842166, 2023). "Normal cells are repaired when damaged through HR, but cancer is fatal when PARP-1 is suppressed because the important proteins for HR, BRCA1 and BRCA2, are broken." (PMID 36902170, 2023). "Mechanistically, blocking PARP1 activity induces SSBs, which are converted to double-stranded breaks (DSB) during DNA replication and leads to synthetic lethality in HR-deficient cancer cells." (PMID 36765038, 2023). "Recruitment of the PARP1 enzyme to DNA damage sites is regulated by SMYD2 methylation at K528, a methyl mark that enhances PARP1 activity in cancer cells." (PMID 37894343, 2023). "Specifically, it has been reported that when PARP1 is aberrantly activated in cancer cells, it blocks phosphorylation of STAT1 and STAT3 via the poly(ADP-ribosyl)ation, ultimately reducing their transcriptional activity." (PMID 37190289, 2023). "PARP1 inhibitors have been used successfully in clinical cancer therapy for decades, but the molecular mechanisms involved remain to be elucidated." (PMID 37808268, 2023). "These primarily function by enhancing the inherent genomic instability of these cancers, leading to the induction of programmed cell death, as PARP1 is a critical sensor and coordinator of DNA double-strand breaks." (PMID 37821462, 2023). "The protein PARP1, which plays a crucial role in DNA repair processes, is an attractive target for cancer therapy, especially for BRCA-deficient cancers." (PMID 36838818, 2023). "Besides, in BRCA-mutated cancers, the deficient of PARP1 could lead to synthetic lethality." (PMID 37365643, 2023). "Pharmacological inhibitors of PARP-1 and -2 have also proven to be beneficial in the treatment of other cancer types such as LC in patients." (PMID 36768904, 2023). "Given the major role of PARP-1 in cancer cells, many pharmacological inhibitors have been designed to set up targeted strategies in the hope of preventing effective DNA repair in these cells." (PMID 37686260, 2023). "The fact that PARP-1 is overexpressed in tumour cells and contributes to vital processes for them suggest the idea of the use of PARP-1 inhibitors (PARPi) to fight cancer." (PMID 36902215, 2023). "Molecular-targeting based therapy in the CRPC setting by PARP inhibitors includes olaparib, a small potent molecule inhibitor of PARP1 and PARP2 enzymes, which causes an accumulation of DNA damage in rapidly dividing cancer cells." (PMID 37958444, 2023). "While many studies have explored PARP-1 as a target for radiosensitization in cancer treatment, considerably fewer have investigated FRT on normal healthy tissue." (PMID 37351512, 2023). "For example, PARP-1 SUMOylation and ubiquitination in PARPi-induced trapping have been shown to dictate the efficacy of PARPi in cancer cells." (PMID 37609662, 2023). "The inhibition of the DNA damage response pathway, including poly (ADP-ribose) polymerase-1 (PARP-1), has been approved to treat several cancers." (PMID 37370065, 2023). "The poly (ADP-ribose) polymerase 1 (PARP1) is a critical component of the cancer biology process through its involvement in replication, transcription, chromatin remodeling, genome maintenance, and DNA repair." (PMID 37005672, 2023). "For example, there was a decrease in expression of a number of anti-cancer genes including pro-apoptotic gene Casp3, DNA repair genes Mgmt and Parp1 and tyrosine phosphatase Ptpn11." (PMID 37886485, 2023).
cancer (continued). "Despite the importance of PARP1/2 inhibitors (PARPis) in cancer treatment and the growing interest in PARG as a therapeutic target, the relative contribution of TARG1 and PARG in the modulation of ADPr levels and cellular homeostasis remains to be elucidated." (PMID 37676774, 2023). "There was a decrease in expression of a number of anti-cancer genes (e.g., Casp3, Mgmt, Parp1, Ptpn11) as well as an increase in several cancer-promoting genes (e.g., Ly6a, Lgr5, Vnn1)." (PMID 38151490, 2023). "Given the success of PARP1 inhibitors in the treatment of certain HRR-defective cancers, fundamental and clinical researchers have been eyeing ways to exploit SL paradigms in the eradication of neoplastic disease." (PMID 38068959, 2023). "As an aside, cancer cells can die in response to specific drugs or drug combinations in a PARP1-dependent fashion." (PMID 36743979, 2023). "We recognize that additional studies in multiple PDD00017273‐resistant human cancer cells using identified gene mutations such as PARG and PARP1 are required to comprehend the mechanisms of PDD00017273 resistance." (PMID 36053937, 2023). "Treatment of NQO1+ cancer cells with a lethal dose of β-lap or DNQ alone induces PARP1 hyperactivation-mediated programmed necrosis (NAD+-Keresis)." (PMID 38136388, 2023). "The introduction of PARP1 inhibitors into therapy, almost ten years ago, has represented a step forward this need being an innovate cancer treatment through a precision medicine approach." (PMID 37570820, 2023). "A clinical-grade PARP1 inhibitor affected the development of cancers in animal models that express miRNA-182." (PMID 37808196, 2023). "We show that targeting the main biosynthesis pathway of PARP1’s substrate in cancer cells works to induce or restore PARPi sensitivity in all models tested, providing robust evidence of this combination’s usefulness both in vitro and in a preclinical model." (PMID 36849518, 2023). "Logically, cancer cells that are treated with DNA damaging agents (such as radiotherapy or chemotherapeutic cytotoxicants such as cisplatin) must activate PARP1 to survive." (PMID 36743979, 2023). "Of note, inhibition of PARP1 does not only have cancer cell-autonomous effects but also stimulates T lymphocyte-mediated anticancer immune response through yet-to-be-elucidated mechanisms." (PMID 36743979, 2023). "HDR defects cause hypersensitivity to the anti-cancer agents camptothecin (CPT), olaparib (a PARP1 inhibitor, PARPi), and cisplatin (a DNA crosslinker)." (PMID 37944988, 2023). "As PARP1 plays a key role in DNA repair and is reported to be upregulated in various cancer cell lines and tumor tissues, PARP1 has been a major target of PARPis in clinical trials." (PMID 37892162, 2023). "Our results point to the exciting possibility of therapeutically targeting the RNF114-mediated PARP1 trapping pathway by nimbolide and its analogs for the treatment of BRCAmut cancers." (PMID 37878693, 2023). "It is important to note that varying cancers display and respond to the expression levels of PARP1 in the cell differently." (PMID 37508568, 2023). "Several PARP1 inhibitors were approved by FDA for the cancer treatment, olaparib being the first one in 2014." (PMID 36982223, 2023). "Inhibiting PARP-1 is lethal in a wide range of cancer cells that lack the homologous recombination repair (HR) pathway." (PMID 37415740, 2023). "The AML had overall gained 4 mutations in cancer genes: ETV1 (p.R405H, VAF 30.4%), KRAS (p.G12A, VAF 27.9%), PARP1 (c.2277 + 1G > C, VAF 7.5%), and ETV6 (p.I358M, VAF 5.3%)." (PMID 38012682, 2023). "Pharmacological PARP1 inhibitors can be used to sensitize cancer cells to chemotherapy and radiotherapy." (PMID 36743979, 2023). "We elected to examine the alternative route for NHEJ dsDNA repair that is mediated by PARP1, which is known to operate in response to oxidative dsDNA damage in mammalian cells and is prone to joining errors, potentially leading to cancer." (PMID 37834296, 2023).